LAPTM4B (lysosomal protein transmembrane 4 beta)
Diseases named in the same sentence as LAPTM4B in open-access papers (continued):
Sharing a sentence is not in itself a finding about the gene and the disease.
breast carcinoma (continued). "LAPTM4B, VEGF, and survivin were over-expressed in breast cancer specimens and highly expressed in MDA-MB-231 cells." (PMID 28476037, 2017). "This study explored the relationships among the expression of LAPTM4B, VEGF, and survivin and clinicopathological characteristics and prognosis in breast cancer patients." (PMID 28476037, 2017). "In particular, the relation of VEGF and survivin protein levels with the expression of LAPTM4B indicates that they could have clinical potential as promising prognostic markers to identify individuals with poor outcomes and may be regarded as therapeutic targets for breast cancer." (PMID 28476037, 2017). "The multivariate analysis showed that high levels of LAPTM4B were an independent prognostic marker for both OS and PFS in breast cancer (P=0.007 and P=0.002, respectively)." (PMID 28476037, 2017). "Therefore, LAPTM4B may also be a potential target for breast cancer therapy." (PMID 22984585, 2012). "In breast cancer, miR-132-3p was found to bind directly to the 3’-UTR of the LAPTM4B gene and acted at the post-transcriptional level to negatively regulate the expression of LAPTM4B." (PMID 40231269, 2025). "Interestingly, some other molecules located in 8q22, including LAPTM4B and YWHAZ, were also identified as key functional molecules for anthracycline resistance and breast cancer recurrence." (PMID 38862581, 2024). "LAPTM4B gene localized in chromosome 8q.22.1, a region containing the MYC oncogene and is amplified in breast cancer and prostate cancer, which prompted us to investigate whether the LAPTM4B copy number is increased in OS." (PMID 37147294, 2023). "miR-489 participates in sensitizing breast cancer cells to chemotherapy through ULK1 downregulation, as well as hampering autophagosome degradation by targeting the lysosomal protein transmembrane 4 beta (LAPTM4B)." (PMID 35309939, 2022). "Similarly, YWHAZ overexpression was significantly associated with reduced disease-free survival/overall survival and earlier time to disease recurrence, and death in breast cancer by combining with elevated levels of Akt, FOXM1, ErbB2, LOC441453 and LAPTM4B 31, 32, 35, 36, 39, 78-80." (PMID 32127952, 2020). "However the exact molecular mechanisms underlying the role of this polymorphism have not been worked out and further investigation of LAPTM4B*2 in breast cancer is warranted." (PMID 22984585, 2012). "The correlations among LAPTM4B, VEGF, and survivin have not been investigated in breast cancer." (PMID 28476037, 2017).
hepatocellular carcinoma (30 papers, 2007 to 2026). A malignant tumor that arises from hepatocytes. "The oncogene LAPTM4B (encoding lysosome-associated protein transmembrane-4β), first cloned in hepatocellular carcinoma cells, is located on chromosome 8q22.1 and encodes two isoforms, LAPTM4B-35 and LAPTM4B-24." (PMID 40231269, 2025). "HDAC2 has been implicated in the malignant phenotype of hepatocellular carcinoma via LAPTM4B activation and in cisplatin resistance in triple-negative breast cancer by modulating m6A-mediated DNA damage repair." (PMID 41444923, 2025). "The oncogene lysosome-associated protein transmembrane-4β (LAPTM4B) was first cloned in hepatocellular carcinoma (HCC), and the polymorphism region in the 5′-UTR of the gene is associated with tumor susceptibility." (PMID 36506911, 2022). "LAPTM4B-35 (NP_060877) is encoded by Lysosomal protein transmembrane 4 beta (LAPTM4B, NM_018407), which was first cloned and found to be a driver gene of hepatocellular carcinoma (HCC) in our laboratory." (PMID 27542271, 2016). "Lysosomal-associated protein transmembrane-4 beta (LAPTM4B) was first cloned in hepatocellular carcinoma (HCC), encoding a type III transmembrane protein with four transmembrane regions." (PMID 23469012, 2013). "Lysosomal protein transmembrane 4 beta (LAPTM4B) is a gene related to hepatocellular carcinoma that has two alleles designated LAPTM4B*1 and LAPTM4B*2." (PMID 22509374, 2012). "Lysosomal-associated protein transmembrane-4 beta (LAPTM4B) was originally identified as a novel oncogene candidate in hepatocellular carcinoma." (PMID 22984585, 2012). "LAPTM4B was first recognized as hepatocellular carcinoma (HCC)-associated gene." (PMID 32102511, 2020). "Lysosome-associated protein transmembrane-4 beta (LAPTM4B) is a novel cancer-related gene that was cloned from hepatocellular carcinoma (HCC) tissues using fluorescence differential display, rapid amplification of cDNA ends (RACE), and reverse transcription polymerase chain reaction (RT–PCR)." (PMID 24746178, 2014). "Previous studies have reported that allelic variant LAPTM4B*2 is associated with genetic susceptibility to gallbladder carcinoma, hepatocellular carcinoma, gastric cancer and colon cancer, and these data suggest that LAPTM4B gene polymorphism plays an important role in carcinogenesis." (PMID 22984631, 2012). "In addition, we recently showed that LAPTM4B allele *2 is a marker of poor prognosis in hepatocellular carcinoma." (PMID 22984631, 2012). "LAPTM4B, an oncogene closely linked to lysosomal function, was first identified in hepatocellular carcinoma (HCC), where its overexpression correlated with poor prognosis and enhances stemness." (PMID 40661135, 2025). "Lysosomal‐associated protein transmembrane‐4 beta (LAPTM4B) is a high‐expression gene in hepatocellular carcinoma (HCC) cells identified by fluorescent‐differential display." (PMID 29337428, 2018). "Lysosome-associated protein transmembrane-4 beta (LAPTM4B) was first identified from hepatocellular carcinoma (HCC), and the LAPTM4B-35 overexpression was associated with poor prognosis of HCC." (PMID 27486880, 2016). "The ensuing hypoxia also upregulates genes operational in lysosomal pathway which includes LAPTM4B, a novel oncogene initially identified in hepatocellular carcinoma but having important role in hypoxia induced autophagy and mitophagy (Lai, Chang & Sun, 2016)." (PMID 30746305, 2019). "The novel lncRNA HCAL promoted hepatocellular carcinoma progression by sponging miR-15a/196a/196b and suppression of LAPTM4B expression." (PMID 30487160, 2018). "Previous studies have proved that LAPTM4B-35 and -24 have different expression status and different roles in tissues and various cell lines of hepatocellular carcinoma." (PMID 27391361, 2016). "LAPTM4B mRNA was originally reported to be overexpressed in human hepatocellular carcinoma and widely expressed in other normal human tissues, including total human ovarian extract." (PMID 25881887, 2015).
hepatocellular carcinoma (continued). "By immunoblotting analysis of hepatocellular carcinoma and normal liver tissue, it was shown that human LAPTM4B was expressed as two isoforms that were translated from alternative ATG codons." (PMID 25881887, 2015). "The LAPTM4B genotype was analyzed by PCR in 68 patients who had undergone curative hepatic resection for hepatocellular carcinoma." (PMID 22509374, 2012). "This study aimed to investigate the correlation of LAPTM4B genotype with prognosis and clinicopathologic features in patients who have undergone resection for hepatocellular carcinoma (HCC)." (PMID 22509374, 2012). "In this study, we tested LAPTM4B genotype by PCR assay in 68 patients who had surgical resection for hepatocellular carcinoma." (PMID 22509374, 2012). "Lysosomal protein transmembrane-4 beta (LAPTM4B) is a cancer-related gene which was originally cloned from hepatocellular carcinoma tissues in our laboratory." (PMID 22984631, 2012). "LAPTM4B mRNA and/or protein was also overexpressed in a wide variety of cancers such as hepatocellular carcinoma, gallbladder carcinoma, uterine cancer, ovarian cancer, extrahepatic cholangiocarcinoma." (PMID 22984585, 2012). "LAPTM4B was originally identified in hepatocellular carcinoma." (PMID 27486880, 2016). "Recently, LAPTM4B (lysosomal protein transmem-brane 4A), which was initially identified as a novel gene upregulated in human hepatocellular carcinoma, was successfully cloned by fluorescence differential display, rapid amplification of cDNA ends, and reverse transcriptase-polymerase chain reaction." (PMID 24651764, 2014). "LAPTM4B was initially identified in hepatocellular carcinoma (HCC) tissues as potentially involved in hepatocyte proliferation or differentiation, showing high expression in HCC tissue cells, but very low expression in normal adult hepatocytes." (PMID 40231269, 2025). "LAPTI, composed of four lysosome‐related genes (CTSV, LAPTM4B, DNAJC6, AP1M2), is a reliable prognostic indicator for hepatocellular carcinoma patients and is validated in external data sets." (PMID 39695350, 2024). "LAPTM4B was first cloned in human hepatocellular carcinoma (HCC) tissues in 2000 and could regulate autophagy and lysosome function." (PMID 32558212, 2020). "In hepatocellular carcinoma (HCC), LAPTM4B also facilitates cell proliferation and tumor growth via AKT signaling pathways." (PMID 32558212, 2020). "In our study, we assessed 6 biomarkers (LAPTM4B, RANKL, OPG, YKL-40, VIT D, and SIRT1), LAPTM4B was first identified as a hepatocellular carcinoma-related gene in mammals." (PMID 32102511, 2020). "In addition, we demonstrated that AP4 promotes hepatocellular carcinoma (HCC) cell proliferation and metastasis and depresses chemotherapy sensitivity via LAPTM4B by activating the PI3K/AKT signalling pathway and caspase‐dependent pathway." (PMID 29337428, 2018). "Hsa-miR-188-5p was shown to inhibit tumor cell proliferation and metastasis in hepatocellular carcinoma through targeting FGF5, and in prostate cancer by repressing LAPTM4B expression." (PMID 29755664, 2018). "However, LAPTM4B *2 is significantly associated with tumor recurrence, poor histopathologic differentiation, higher TNM stage and presence of portal vein invasion which argues that it is a driver of hepatocellular carcinoma and therefore warrants further investigation." (PMID 22509374, 2012). "It has been revealed that transfection of the LAPTM4B gene promoted anchorage-independent growth and colony formation of HLE cells, whereas anti-sense oligonucleotides against LAPTM4B inhibited proliferation of BEL-7402, a hepatocellular carcinoma cell line in which LAPTM4B expression was found." (PMID 24651764, 2014). "Moreover, AP4 regulates LAPTM4B, and activates the PI3K/AKT signaling pathway and glycogen synthase kinase 3 beta (GSK3b), leading to c-myc accumulation, which amplified the effect of the PI3K/AKT pathway on the drug resistance of hepatocellular carcinoma cells." (PMID 40231269, 2025).
prostate carcinoma (13 papers, 2015 to 2025). A carcinoma that arises from epithelial cells of the prostate gland. "The Spearman correlation analysis suggested the HIF-1α expression to be significantly associated with increased MDR1 and LAPTM4B expression in breast, ovarian, colon and prostate cancer patients." (PMID 30746305, 2019). "Association analysis between HIF-1α, MDR1 and LAPTM4B expression in prostate cancer blood specimens." (PMID 30746305, 2019). "It would be worth noting that LAPTM4B-35, a protein encoded by LAPTM4B, is highly expressed in various solid tumors, and its overexpression is associated with poor prognosis in many malignancies, including ovarian, breast, cervical, and prostate cancers." (PMID 36937841, 2023). "To this end, we selected Hela, A431, and PC3 as representative cells to investigate the potential involvement of LAPTM4B in cervical cancer, epidermoid cancer, and prostate cancer." (PMID 38902268, 2024). "The expression of HIF-1α, MDR1 and LAPTM4B was studied in blood of 72 breast, 42 ovarian, 32 colon and 21 prostate cancer patients through real time PCR analysis using delta cycle threshold method." (PMID 30746305, 2019). "A similar pattern of linear correlation was also found among HIF-1α, MDR1 and LAPTM4B in case of prostate cancer (R = 0.806, p < 0.001) with 12 patients having high expression of these genes while six patients having low expression of these genes." (PMID 30746305, 2019). "Correlation of HIF-1α, MDR1, and LAPTM4B expression with clinico-pathological features of prostate cancer." (PMID 30746305, 2019). "In prostate cancer, we observed an association of increased HIF-1α and LAPTM4B expression with advanced tumor stage and metastasis." (PMID 30746305, 2019). "miR‐188 was reduced in prostate cancer and retarded cancer cell growth via repression of LAPTM4B." (PMID 32592428, 2020). "Moreover, other studies have demonstrated that LAPTM4B has been upregulated in many human cancers, such as lung cancer, gastric cancer, and prostate cancer, and is known to have a role as a dynamic cancer-associated biomarker that is involved in several biological processes." (PMID 32102511, 2020). "In addition, miR-188-5p could also inhibit the expression of LAPTM4B by binding to its 3’-UTR region, thus inhibiting cell proliferation and invasion in prostate cancer." (PMID 40231269, 2025).
gastric cancer (12 papers, 2012 to 2025). A primary or metastatic malignant neoplasm involving the stomach. "Association between LAPTM4B-35 expression and clinicopathological features of patients with gastric carcinoma in testing cohort." (PMID 25689860, 2015). "Association between LAPTM4B-35 expression and clinicopathological features of patients with gastric carcinoma in discovery cohort." (PMID 25689860, 2015). "Previous studies have shown that LAPTM4B polymorphisms are associated with increased risk for gallbladder carcinoma, gastric cancer, colon cancer and liver cancer in Chinese patients." (PMID 22984631, 2012). "Previous studies have shown that LAPTM4B polymorphisms are associated with increased risk for gastric cancer and cervical cancer in Chinese patients." (PMID 22509374, 2012). "Furthermore, in patients with gastric cancer, we have found that even though LAPTM4B genotype was correlated with susceptibility of gastric cancer, this polymorphism did not correlate with prognosis (data unpublished)." (PMID 27391361, 2016). "Increased LAPTM4B expression has been observed in various cancers, including breast, liver, lung, ovarian, uterine, and gastric cancers." (PMID 40092987, 2025). "Following transfection with pcDNA3.0-AF and hCas9/gRNA, we performed wound-healing assay to analyze the migration ability of LAPTM4B-35 over-expression/knockdown gastric cancer cells." (PMID 25849595, 2015). "LAPTM4B-35 positive expression in gastric cancer tissues correlated with the poor outcome and proved to be an independent prognostic factor in subgroup of GC patient in TNM stages I-III or without lymphovascular invasion." (PMID 25849595, 2015). "In our present study, the function of LAPTM4B in gastric cancer was investigated by in vitro assays." (PMID 25849595, 2015). "Relationship between LAPTM4B-35 Expression and Clinicopathological Features of Patients with Gastric Cancer." (PMID 25849595, 2015). "Multivariate Cox regression analysis in this subgroup demonstrated that among all analyzed factors, LAPTM4B-35 expression is an independent prognostic factor in gastric cancer patients in TNM stages I-III but in stage IV." (PMID 25849595, 2015). "In the present research, we detected LAPTM4B-35 expression status in precancerous gastric lesions and gastric carcinomas by immunohistochemical staining." (PMID 25689860, 2015). "LAPTM4B-35 expression was an independent prognostic indicator for the overall survival of patients with gastric carcinoma in both cohorts." (PMID 25689860, 2015). "Kaplan-Meier survival curves and univariate analysis showed that expression of LAPTM4B-35 had a significant impact on overall survival of patients with gastric carcinoma in discovery cohort (P<0.001) and testing cohort (P = 0.001)." (PMID 25689860, 2015). "The present research demonstrated that LAPTM4B-35 over-expression was an independent factor in gastric carcinoma prognosis." (PMID 25689860, 2015). "The correlation between the expression of LAPTM4B-35 and clinicopathologic characteristics of patients with gastric carcinoma was analyzed using chi-square test." (PMID 25689860, 2015). "Furthermore, we also analyzed the correlation of LAPTM4B-35 expression with clinicopathological parameters in gastric cancer." (PMID 25849595, 2015). "Moreover, immunohistochemical analysis in 180 pairs of gastric cancer showed LAPTM4B-35 was overexpressed in GC tissues (68.3%) compared with their paired noncancerous mucosa (16.1%)." (PMID 25849595, 2015). "LAPTM4B gene may be a useful target of interventions slowing the progression of precancerous gastric lesions and a new therapy method to improve the prognosis of gastric carcinoma." (PMID 25689860, 2015). "Expression of LAPTM4B-35 in normal gastric mucosa, CAG, IM, IM beside GC, dysplasia and gastric carcinoma." (PMID 25689860, 2015).
gastric cancer (continued). "Similarly, earlier work has demonstrated that EGFR was co-immunoprecipitated with endogenous LAPTM4B and LAPTM4B overexpression correlates with EGFR activation in gastric cancer cells." (PMID 30940109, 2019). "However the expression of LAPTM4B-35 and its role in the progression of gastric cancer (GC) remains unknown." (PMID 25849595, 2015). "However, in gastric cancer, it has been proposed that Beclin 1 interacts with both the N- and C-terminus of LAPTM4B and that this interaction is not dependent on the Vps34 complex." (PMID 40231269, 2025). "In this study, we investigated LAPTM4B-35 expression in 24 gastric cancer and their paired noncancerous gastric surgical specimens by qRT-PCR and found that LAPTM4B-35 mRNA expression level in gastric cancer was significantly elevated compared with that in the paired noncancerous tissue group." (PMID 25849595, 2015).
liver cancer (10 papers, 2012 to 2025). An epithelial or non-epithelial malignant neoplasm that arises from the liver. "This support from our meta-analysis indicates that the LAPTM4B polymorphism is a possible susceptibility factor for multiple cancers in the Chinese population, especially for liver cancer and GC." (PMID 24746178, 2014). "More importantly, our study revealed for the first time that CLN3, GBA, and LAPTM4B are specifically expressed in hepatocytes in the liver and promote the progression of liver cancer through multiple tumor-related pathways." (PMID 38114725, 2023). "A study on liver cancer has shown that the PPRP motif in the N-terminal region of LAPTM4B plays a key role in promoting tumor cell proliferation, migration, and invasion." (PMID 32651973, 2021). "A recent publication reported that ETV1 might contribute to the aggressiveness of liver cancer stem cells by regulating LAPTM4B, a factor involved in tumour cell proliferation and metastasis." (PMID 40275610, 2025). "Western-blotting was conducted for ETV1 and LAPTM4B expression in liver cancer cells." (PMID 38388484, 2024). "LAPTM4B overexpression promotes liver cancer stem cell (LCSC) proliferation and MDSC migration." (PMID 38388484, 2024). "Understanding the molecular mechanisms of CLN3, GBA, and LAPTM4B in liver cancer cells may help to develop new therapeutic targets for liver cancer." (PMID 38114725, 2023). "Of note, CLN3, GBA, and LAPTM4B were specially expressed in Hepatocytes, which may be novel biomarkers for liver cancer Hepatocytes." (PMID 38114725, 2023). "Therefore, CLN3, GBA, and LAPTM4B may be involved in cancer progression of liver cancer hepatocytes." (PMID 38114725, 2023). "Our mechanistic investigations identified LAPTM4B as a crucial gene regulated by ETV1 (a transcription factor), especially in liver cancer stem cells (LCSCs)." (PMID 38388484, 2024).